CD47 (CD47 molecule)
Diseases named in the same sentence as CD47 in open-access papers (continued):
Sharing a sentence is not in itself a finding about the gene and the disease.
melanoma (continued). "Of note, not all primary melanoma cell cultures of post-vemurafenib treatment biopsies expressed increased levels of CD47." (PMID 29050218, 2017). "Similar negative correlations between PATZ1 and CD47 mRNA expression were found in TCGA datasets for melanoma (−0.41), head and neck squamous cell carcinoma (−0.46), and bladder carcinoma (−0.49)." (PMID 26840086, 2016). "NDV-mediated CD47 blockade did not improve animal survival in B16-F10 melanoma nor KPC pancreatic ductal adenocarcinoma (PDAC), but greater incidence of tumor clearance resulting in immunological memory was observed in PDAC compared to B16-F10 tumor-bearing mice." (PMID 41322194, 2025). "It is unclear whether the decrease in tumor growth observed upon CD47 blockade in melanoma models is dependent or independent of T cells." (PMID 38414061, 2024). "We reveal that it is mediated by a significant increase in chromatin accessibility at CD47 prmoter region, including elevated levels of epigenetic histone modifications at H3K4Me3 residues, in melanoma but not in normal melanocytes or HepG2 cells which are known for low CD47 expression." (PMID 39742254, 2024). "Although the loss of either CD47 or TSP1 in the tumor microenvironment greatly enhanced tumor ablation by ionizing radiation in several immune-competent cancer models, we also found that, in the absence of tumor irradiation, B16 melanomas grew moderately faster in cd47−/− mice." (PMID 36768931, 2023). "Here we report the anticancer efficacy of an oncolytic MyxV simultaneously expressing CD47, to avoid an antiviral immune response, and IFN-γ, to boost effective anti-tumoral immunity as a stand-alone treatment, or with αPD-L1 combination therapy in melanoma models." (PMID 37835397, 2023). "Because CD47 is also expressed on macrophages, linking anti-PD-1/PD-L1 therapy with anti-CD47/SIRPα as a fusion protein may be beneficial for CTCL treatment, as it has been shown to have good efficacy against melanoma in vitro, even when anti-PD-L1 monotherapy alone was insufficient." (PMID 36429020, 2022). "Studies in preclinical models with cancer types including chronic lymphocytic leukemia, colon cancer, melanoma, HNSCC, and glioblastoma, showed the induction of antitumor cytotoxic T cell populations, and reduced regulatory T cell populations in response to anti-CD47 treatment." (PMID 34944850, 2021). "Therefore, CD47 positively and negatively regulates NK cell function, and therapeutic antibodies that block inhibitory TSP1-CD47 signaling can enhance NK immune surveillance of melanomas." (PMID 33925464, 2021). "The employment of anti-CD47 siRNA delineates that CD47 blockade can restrain lung metastasis stemming from melanoma since the lack of CD47 expression on macrophages augments these immune cells phagocytosis and its expression is increased during metastasis development." (PMID 32902664, 2021). "In addition, the combination of a tumour-specific antibody with CD47 blockade failed to meaningfully enhance the phagocytosis of three human melanoma cell lines, although SKMEL28 cells were sensitive to phagocytosis with an opsonizing antibody." (PMID 31205227, 2020). "Additionally, CD47 blockade failed to promote anti-melanoma immune responses or tumour regression in vivo." (PMID 31205227, 2020). "Notably, our analysis in melanoma patients also unravelled a positive correlation between CD47 and BNIP3 transcript levels, suggesting that the hypoxia-responsive protein BNIP3 may be a modulator of the phagocytic barrier in melanoma cells." (PMID 29707136, 2018). "This suggests that resistance to vemurafenib of melanomas without upregulation of CD47 may be primarily due to mechanisms other than reactivation of ERK, such as overexpression of MAP3K8 (COT) and switch of melanoma cells towards a more mesenchymal phenotype." (PMID 29050218, 2017).
melanoma (continued). "Thus, we focused our efforts on improving CAR-M-mediated phagocytosis of melanoma cells by engineering the CSPG4-targeting chimeric antigen receptor to contain the intracellular FcRγ phagocytic signaling domain and combining the CSPG4-targeting CAR-Ms with CD47 blocking antibodies." (PMID 40082557, 2025). "In this report, we present evidence that upregulation of CD47 expression is an important immunosuppressive mechanism triggered by BRAF/MEK inhibitors that prevents macrophage phagocytosis of melanoma cells, and may thus contribute to impairment of anti-melanoma T cell responses." (PMID 29050218, 2017). "Similar results were observed in the B16F10 model, in which vaccination (i.s.)with anti-CD47 Ab-coated, but not non-coated, tumor cells, induced a significant antitumor response against B16F10 melanoma compared to the medium controls." (PMID 31996683, 2020). "For instance under normoxic conditions, despite having very low ecto-CD47, the BNIP3KD B16-F10 melanoma cells were not readily phagocytosed by macrophages." (PMID 29707136, 2018). "As A375 melanoma cells did not form spheroids, 3D tumors were developed on fertilized avian eggs, also known as an in ovo tumor model, using the chick chorioallantoic membrane (CAM) assay to further investigate the effects of NTP on CD47." (PMID 33540720, 2021). "This melanoma resistance to phagocytosis was not mediated by soluble factors, and it was unaffected by siRNA-mediated knockdown of 47 prospective ‘don’t eat me’ signals or by CRISPR-Cas-mediated CD47 knockout." (PMID 31205227, 2020). "Nevertheless, the apparent dispensability of CD47 and the absence of ecto-CALR, despite on-going phagocytosis, may be a sign of B16-F10 melanoma cells utilizing either alternative ‘don’t eat me’ signals or highly potent ‘eat me’ signals capable of circumventing ecto-CD47." (PMID 29707136, 2018). "Thus, B16-F10 melanoma-specific BNIP3 ablation in combination with hypoxia, stimulates phagocytic clearance of melanoma cells by macrophages, although this does not inversely correlate with the ecto-CD47 levels." (PMID 29707136, 2018).
glioblastoma (105 papers, 2012 to 2026). The most malignant astrocytic tumor (WHO grade IV). "In glioblastoma, CD47 overexpression has been reported to be associated with poor progression-free and overall survival." (PMID 38786045, 2024). "In general, increased CD47 expression on tumor cells is associated with a worse prognosis in glioblastoma." (PMID 36986829, 2023). "Here, leveraging these radiotherapy-elicited processes, we generate a bridging-lipid nanoparticle (B-LNP) that engages tumor-associated myeloid cells (TAMCs) to glioblastoma cells via anti-CD47/PD-L1 dual ligation." (PMID 36959214, 2023). "CD47 is an integrin-associated protein that is frequently over-expressed in various tumors including glioblastomas." (PMID 29899856, 2018). "Macrophage polarization state may also be altered by anti-CD47 therapy and one study of glioblastoma found that CD47 blockade converts tumor-associated macrophages into an anti-tumor state and increases macrophage recruitment into the tumor." (PMID 32082311, 2020). "Our results demonstrated a pronounced correlation between αvβ3 and CD47 surface expression in the majority of tumor‐derived lines (R2 = 0.830, p < 0.001), including those of colorectal, lung, glioblastoma, and breast origin." (PMID 41168993, 2026). "In lipid metabolism, inhibition of fatty acid oxidation (e.g., with the CPT1 inhibitor etomoxir) was shown to synergize with CD47-blocking antibodies and radiotherapy to enhance anti-tumor effects in a mouse glioblastoma (GBM) model." (PMID 40356913, 2025). "Specific inhibition of the THBS1/CD47 interaction using an antagonist peptide decreases cell invasion in glioblastoma." (PMID 41019041, 2025). "In a mesenchymal glioblastoma model, CD47 knockout via lipid nanoparticles enhances immune cell infiltration and reduces tumor growth." (PMID 39888280, 2025). "In glioblastomas, the CD47 pathway has been shown to significantly enhance M1-mediated phagocytosis of glioma cells, resulting in slowed tumor growth and prolonged survival times, with minimal to no side effects observed in both in vitro and in vivo models." (PMID 40867316, 2025). "We further probed the role of HIF-1α in regulating CD47 protein in glioblastoma using a migration assay." (PMID 39781344, 2025). "CD47 has been confirmed to promote the invasion of glioblastoma and endometrial carcinoma cells via the PI3K/AKT/mTOR-mediated glycolysis pathway." (PMID 38317230, 2024). "Overexpression of CD47 is also stated in acute myeloid leukemia stem cells as well as in patients with glioblastoma, ovarian, breast, bladder, colon, and hepatocellular cancer." (PMID 38892394, 2024). "In a human glioblastoma xenograft model, anti-CD47 induced M1 polarization of macrophages within the TME and prolonged survival." (PMID 38786045, 2024). "Contrary to clonotypic homogeneous glioma cell lines where CD47 is consistently highly expressed, newly diagnosed glioblastoma specimens exhibited heterogeneous and very low expression of CD47." (PMID 38786045, 2024). "In the CT2A immunocompetent glioblastoma model, OV-anti-CD47 increased TAM phagocytic activity and increased survival compared to mice treated with the native virus." (PMID 39196415, 2024). "More interestingly, the combination of Dox@HFn Gel with anti‐CD47 antibody (αCD47) significantly extended mice survival in the orthotropic glioblastoma tumor model." (PMID 38029345, 2024). "In contrast, critical biomarkers for glioblastoma, including CD47 and SIRPα, exhibited higher expression among these immune checkpoints, which are correlated with a CRG low-risk signature and improved prognosis." (PMID 38956740, 2024). "Enhanced fatty acid metabolism promotes invasive growth in glioblastoma (GBM) along with CD47‐mediated immune evasion." (PMID 39415848, 2024). "In vitro, OV-anti-CD47 increased phagocytic activity of human macrophages against glioblastoma cells through antibody dependent phagocytosis mediated by the Fc portion of the secreted IgG1." (PMID 39196415, 2024).
glioblastoma (continued). "The CD47-SIRPα axis represents a novel target for treating glioblastoma based on the encouraging outcomes in preclinical models of gliomas." (PMID 38786045, 2024). "A key consideration is how closely these models recapitulate the biology of human glioblastoma from both the perspective of myeloid infiltration and location and that of CD47 expression levels and heterogeneity." (PMID 38786045, 2024). "For example, since the CD47/SIRPα axis resides at the infiltrating margin of glioblastoma, including the adjacent microglia population, these regions typically have an intact BBB." (PMID 38786045, 2024). "Anti-CD47 antibodies can induce M1-like TAM development in tumor tissue and decrease tumor growth in a mouse model of non-small cell lung cancer, and CD47 inhibition can switch TAM from a pro-tumor morphology to an anti-tumor phenotype in glioblastoma." (PMID 37138860, 2023). "Despite these limitations, the inhibition of CD47 in human tumor xenografts has proven to be effective, impairing the growth of lymphoma, leukemia, glioblastoma, breast, colon, ovarian, and lung cancer models." (PMID 37958404, 2023). "Elevated LRIG2 (Leucine Rich Repeats And Immunoglobulin Like Domains 2) gene expression in glioblastoma cells triggers CD47 upregulation and activates the CD47-SIRPα anti-phagocytic axis." (PMID 37700840, 2023). "Microglia and monocytes are the effector cells of CD47-SIRPα antiphagocytic axis disruption against glioblastoma." (PMID 37063864, 2023). "In mice, depleting CD47 increases the phagocytosis of macrophages and limits glioblastoma tumour progression." (PMID 38136335, 2023). "Recent studies reported that disrupting the CD47–TSP-1 interaction reduced angiogenesis in neuroblastoma and glioblastoma models, but selectively depleting CD47 in stromal cells increased angiogenesis and tumor burden in a syngeneic prostate cancer model." (PMID 37958404, 2023). "As a key component of the standard of care for glioblastoma, radiotherapy induces several immune resistance mechanisms, such as upregulation of CD47 and PD-L1." (PMID 36959214, 2023). "By targeting the CD47-SIRPα immunological checkpoint glioblastoma development can be inhibited and the activity of phagocytic, dendritic and T-lymphocytes enhanced promoting clearance of tumour cell in innate and adaptive immunity." (PMID 36674659, 2023). "Although the EGFR-CD47 axis was primarily defined using glioblastoma models, it likely operates in NSCLC as EGF stimulation induced CD47 expression in A549 cells and CD47 positivity is associated with EGFR-mutant LUAD." (PMID 37958404, 2023). "The study discusses the prospects of using antibodies targeting CD47 or CD24 in the treatment of glioblastoma." (PMID 37900496, 2023). "Preclinical studies also investigated the potential of combining CD24 and CD47 for the treatment of glioblastoma." (PMID 37846296, 2023). "Here, the authors show that radioresistant glioblastoma boosts mitochondrial fatty acid oxidation that fuels cell proliferation and induces immunosuppression via CD47 mediated anti-phagocytosis." (PMID 35314680, 2022). "qRT-PCR and Western blotting were adopted to examine CD47 expression in glioblastoma cells treated with 4MU." (PMID 35410993, 2022). "Some research groups have engineered oHSV1 expressing a full-length CD47 antibody, which has achieved good therapeutic efficacy in mouse models of metastatic ovarian cancer and glioblastoma." (PMID 36310169, 2022). "For instance, antibodies against CD47 or CD24 have been proposed as new targets for glioblastoma therapy." (PMID 35822692, 2022). "Our observations confirmed that after glioblastoma cells were treated with 4MU for 48 h, the expression level of CD47 was significantly reduced, and this inhibitory effect was reversed by exogenous HA." (PMID 35410993, 2022).
glioblastoma (continued). "By inhibiting HA synthesis in glioblastoma cells with 4MU, we found that the expression level of CD47 was decreased in glioblastoma cells and that SIRPα expression was increased in macrophages." (PMID 35410993, 2022). "CD47 blockade by using anti-CD47 antibody was reported to stimulate phagocytosis of glioblastoma by macrophages and hence reduce tumor burden in vivo." (PMID 35428347, 2022). "Other research groups further report that inhibiting CD47 on murine macrophages in glioblastoma results in an elevated M1:M2 ratio and thereby an inflammatory immune reaction against tumor cells." (PMID 35418973, 2022). "Inhibition of FAO by etomoxir combined with anti-CD47 antibodies sensitizes glioblastoma to radiotherapy." (PMID 35314680, 2022). "CD47 is highly expressed in several human cancer types, such as non-Hodgkin's lymphomas, myeloid leukaemia, glioblastoma, leiomyosarcoma 35-38." (PMID 34093795, 2021). "Authors here show that oncolytic viruses expressing anti-CD47 antibodies improve glioblastoma survival in mouse models." (PMID 34625564, 2021). "A similar event was also observed in glioblastoma, where cells overexpressing CD47 displayed increased Akt activation and invasion ability." (PMID 34768921, 2021). "For example, a recent study in human and mice glioblastoma cell lines showed that the combined CD47 blockade with temozolomide resulted in a pro-phagocytosis effect against tumorigenic cells compared with normal astrocytes." (PMID 34203368, 2021). "The clinical analysis shows that CD47 is highly expressed on multiple types of cancer patients including glioblastoma, ovarian, breast, bladder, colon, and hepatocellular carcinoma, which correlates with low survival." (PMID 34512146, 2021). "CD47 blockade has remarkable therapeutic efficacy in various preclinical models of bladder, colon and breast cancer, glioblastoma, lymphoma, and acute lymphocytic leukemia." (PMID 33956406, 2021). "Here we show locoregional control of glioblastoma by an oncolytic herpes virus expressing a full-length anti(α)-human CD47 IgG1 or IgG4 antibody." (PMID 34625564, 2021). "From the translation perspective, the combined application of CD24 antibody with the CD47 antibody offers an additive effect against glioblastoma compared to either treatment alone." (PMID 34363319, 2021). "Since single immunotherapy cannot target many pathways, it is reasonable that the development of clinical immunotherapy for glioblastoma, including the use of CD47 antibodies, has progressed slowly." (PMID 34363319, 2021). "Here, the authors show that in glioblastoma mouse models, temozolomide improves the phagocytosis effect of CD47 blockade in APCs and results in the activation of adaptive anti-tumour responses." (PMID 32198351, 2020). "suggest that surgical resection combined with anti-CD47 immunotherapy was shown to promote the recruitment of macrophages and promote phagocytosis of glioblastoma." (PMID 33329583, 2020). "When neural progenitor cells were offered as targets, phagocytosis by M1 or M2 subsets after anti-CD47 treatment was less than that observed towards glioblastoma." (PMID 27092773, 2016). "Notably, targeting the CD47-SIRPα interaction enhances phagocytosis, a finding also demonstrated in mouse and human M1 and M2 macrophages within a glioblastoma model." (PMID 40724825, 2025). "Notably, ETO combined with anti-CD47 antibody therapy synergistically enhances macrophage-mediated tumor clearance in radiation-resistant glioblastoma." (PMID 41219902, 2025). "The CD47 protein is highly expressed in various types of cancers, including acute and chronic myeloid leukemia, non-Hodgkin lymphomas, multiple myeloma, leiomyosarcoma, glioblastoma, and carcinomas of the bladder, ovary, prostate, breast, and colon." (PMID 39795582, 2024).